LIMS4 (LIM zinc finger domain containing 4)
Synonyms: LIMS3L
Tractability: No criterion of Open Targets' tractability assessment is met for any kind of drug.
Gene: Protein-coding gene on chromosome 2 (110,445,883 to 110,473,075, reverse strand). Ensembl gene ENSG00000256671.
Subcellular location (Human Protein Atlas): Cytosol; Focal adhesion sites
Gene Ontology:
Molecular function: protein binding
Homologues: Orthologues: macaque LIMS1 (98% identical), dog LIMS1 (96% identical), mouse Lims1 (96% identical), rat Lims1 (94% identical), guinea pig Lims1 (92% identical), tropical clawed frog lims1 (84% identical), zebrafish lims1 (74% identical), zebrafish lims2 (70% identical), Drosophila melanogaster stck (55% identical), Caenorhabditis elegans unc-97 (48% identical), Caenorhabditis elegans pin-2 (32% identical), Drosophila melanogaster Zasp67 (21% identical). Paralogues in human: LIMS3 (100% identical), LIMS1 (77% identical), LIMS2 (68% identical).